LINC01787 (long independently transcribed non-coding RNA 1787)
Gene: Long non-coding RNA gene on chromosome 1 (96,254,069 to 96,374,125, reverse strand). Ensembl gene ENSG00000231987.
Diseases named in the same sentence as LINC01787 in open-access papers:
LINC01787 is named in the same sentence as 3 diseases in open-access papers, as found by Europe PMC text mining. Sharing a sentence is not in itself a finding about the gene and the disease. The quoted sentences say what the papers report.
breast carcinoma (1 paper, 2019). "The result also showed that high expression of LINC01787 was associated with poor prognosis of breast cancer patients." (PMID 31750242, 2019). "In this study, we further investigated the expression, clinical association, roles, and functional mechanisms of LINC01787 in breast cancer." (PMID 31750242, 2019). "EdU incorporation assays also revealed that LINC01787 overexpression promoted breast cancer cell proliferation, which was abolished by the mutation of pre-miR-125b binding sites." (PMID 31750242, 2019). "Functional assays showed that LINC01787 promotes breast cancer cell proliferation and migration and breast cancer xenograft growth in vivo, which is abolished by the mutation of pre-miR-125b binding sites on LINC01787 or overexpression of miR-125b." (PMID 31750242, 2019). "The expression of LINC01787 is inversely associated with that of miR-125b in breast cancer tissues." (PMID 31750242, 2019). "Furthermore, LINC01787 is up-regulated in breast cancer tissues and is associated with advanced stages and poor survival." (PMID 31750242, 2019). "Due to LINC01787 repressing miR-125b generation and miR-125b has tumor suppressive roles in breast cancer, we next investigated the roles of LINC01787 in breast cancer." (PMID 31750242, 2019). "Functional assays showed that overexpression of LINC01787 enhances the proliferation and migration of breast cancer cells, and conversely knockdown of LINC01787 represses the proliferation and migration of breast cancer cells." (PMID 31750242, 2019). "Our data revealed that the expression of miR-125b was significantly inversely correlated with that of LINC01787 in breast cancer tissues." (PMID 31750242, 2019). "The correlation between LINC01787 expression level and prognosis of these 89 breast cancer patients showed that breast cancer patients with high LINC01787 expression level had worse prognosis that those with low LINC01787 expression level." (PMID 31750242, 2019). "The results showed that the number of molecules of LINC01787 was comparable with that of pre-miR-125b-1 and pre-miR-125b-2 in breast cancer cells, which support the effects of LINC01787 on pre-miR-125b via direct interaction." (PMID 31750242, 2019). "Our results thus suggests that LINC01787 is a potential prognostic biomarker and therapeutic target for breast cancer." (PMID 31750242, 2019). "Collectively, these data suggested that miR-125b overexpression reverses the oncogenic roles of LINC01787 in breast cancer." (PMID 31750242, 2019). "Our data suggests LINC01787 as a potential prognostic biomarker and therapeutic target for breast cancer." (PMID 31750242, 2019). "EdU incorporation assays also revealed that enhanced expression of miR-125b reversed the pro-proliferative roles of LINC01787 in breast cancer." (PMID 31750242, 2019). "In conclusion, our findings identified a novel up-regulated and oncogenic lncRNA LINC01787 in breast cancer, which binds pre-miR-125b and represses mature miR-125b generation." (PMID 31750242, 2019). "The mutation of the pre-miR-125b binding sites on LINC01787 abolished the roles of LINC01787 in promoting breast cancer cell proliferation, migration, and in vivo xenograft growth." (PMID 31750242, 2019). "EdU incorporation assays also revealed that LINC01787 knockdown reduced breast cancer cell proliferation." (PMID 31750242, 2019). "Moreover, both pre-miR-125b and LINC01787 were mainly located in the cytoplasm in breast cancer cells, which support the potential interaction between LINC01787 and pre-miR-125b." (PMID 31750242, 2019). "Furthermore, overexpression of miR-125b also abolished the roles of LINC01787 in promoting breast cancer cell proliferation, migration, and in vivo xenograft growth." (PMID 31750242, 2019). "Our data also suggested that LINC01787 is a potential therapeutic target for breast cancer." (PMID 31750242, 2019).
breast carcinoma (continued). "To further elucidate whether the oncogenic roles of LINC01787 in breast cancer are dependent on the negative regulation of miR-125b, we stably overexpressed miR-125b in LINC01787 stably overexpressed MDA-MB-231 cells." (PMID 31750242, 2019). "Thus, we identified that LINC01787 plays key oncogenic roles in breast cancer." (PMID 31750242, 2019). "Furthermore, we also found that LINC01787 promotes breast cancer xenograft growth in vivo." (PMID 31750242, 2019).
cancer (1 paper, 2019). A tumor composed of atypical neoplastic, often pleomorphic cells that invade other tissues. "The expression and roles of LINC01787 in cancers are still unknown." (PMID 31750242, 2019).
LINC01787 also shares sentences with these, for which no sentence is quoted: tumor (1 paper).